FAM229B (family with sequence similarity 229 member B)
Synonyms: C6orf225; DKFZp586F0922; LOC619208
Tractability: No criterion of Open Targets' tractability assessment is met for any kind of drug.
Gene: Protein-coding gene on chromosome 6 (112,087,122 to 112,104,223, forward strand). Ensembl gene ENSG00000203778.
Subcellular location (Human Protein Atlas): Nucleoplasm; Golgi apparatus; Nucleoli
Gene Ontology:
Molecular function: protein binding
Genetic constraint (gnomAD): Loss-of-function variants: 0 observed, 5.21 expected, observed/expected ratio (o/e) 0, 90% interval 0 to 0.57. That is too few expected variants to judge how well the gene tolerates losing a copy. Missense variants: 82 observed, 91.32 expected, observed/expected ratio (o/e) 0.9, 90% interval 0.75 to 1.08. Synonymous variants: 27 observed, 33.39 expected, observed/expected ratio (o/e) 0.81, 90% interval 0.6 to 1.12.
Homologues: Orthologues: chimpanzee FAM229B (98% identical), macaque FAM229B (95% identical), dog FAM229B (94% identical), pig FAM229B (91% identical), mouse Fam229b (90% identical), rat Fam229b (90% identical), rabbit FAM229B (89% identical), guinea pig FAM229B (76% identical). Paralogues in human: FAM229A (39% identical).
Diseases named in the same sentence as FAM229B in open-access papers:
FAM229B is named in the same sentence as 2 diseases in open-access papers, as found by Europe PMC text mining. Sharing a sentence is not in itself a finding about the gene and the disease. The quoted sentences say what the papers report.
cervical adenocarcinoma (1 paper, 2020). An adenocarcinoma arising from the cervical epithelium. "MiRNA-mRNA interactions by miranda and targetscan analysis showed that the downregulated expression of CADM1, SBSPON, and FAM229B in cervical adenocarcinoma samples might be the potential target genes for miR-192-5p." (PMID 33024199, 2020).
adenocarcinoma (1 paper, 2020). A common cancer characterized by the presence of malignant glandular cells. "The potential predicted targets of miR-192-5p include CADM1, SBSPON and FAM229B, which were down-regulated in adenocarcinoma from our transcriptome sequencing data." (PMID 33024199, 2020).